CD40 (CD40 molecule)
Diseases named in the same sentence as CD40 in open-access papers (continued):
Sharing a sentence is not in itself a finding about the gene and the disease.
tumor (continued). "The functional enrichment analysis revealed that tumor cells, even under chemotherapy treatment, contain proteins involved in processes like migration, cytoskeleton locomotion, and cell adhesion (ICAM, plexin, IL-16, CD40, ARPs, and ezrin)." (PMID 36611989, 2023). "In contrast, the addition of anti-CD40 was required to achieve control of a non-irradiated subcutaneous tumor in AT3-bearing mice treated with RT+CTLA4i." (PMID 37620372, 2023). "Consequently, soluble CD40/CD40L alone or as an adjunct to chemotherapy in ovarian and breast cancers was found to significantly hinder tumor growth and increase patient OS." (PMID 37174089, 2023). "In this study, we investigated the efficacy and mechanism of action of rWTC-MBTA, an autologous whole tumor cell vaccine consisting of irradiated tumor cells (rWTC) pulsed with mannan-BAM, TLR agonists, and anti-CD40 antibody (MBTA), in preventing tumor metastasis in multiple animal models." (PMID 37434263, 2023). "The co-culture of live LN-229 with parental HMC3, SIRPα-negative and MERTK-negative cells yielded low % GFP+ CD40+ cells (~5%), indicating low activities of tumor phagocytosis." (PMID 37483607, 2023). "Whereas the addition of anti-CD40 dramatically improved the rejection of the irradiated tumor it did not further improve the inhibition of lung metastases achieved by RT+CTLA4i in 4T1 bearing mice." (PMID 37620372, 2023). "We observe that CD8 T cells may be a sufficient source of CD40L to activate CD40-expressing cells and in turn support CD8 differentiation into CD103+ cells in the tumor environment." (PMID 37072485, 2023). "The killing effect of BCR and some costimulatory molecules, such as CD40 and CD86, on the surface of B cells in response to external antigen stimulation or enhancement of costimulatory signals of CD4+ T cells in tumours can also be used as markers for clinical prognostic monitoring." (PMID 36890557, 2023). "A study in a murine model demonstrated that neutrophils may be helpful in tumor elimination and metastasis reduction from the combined actions of TNF-α, CD40 agonist, and tumor-binding antibody." (PMID 37631922, 2023). "The cluster of differentiation 40 (CD40) molecule, a TNF-α receptor family member and receptor for CD40 ligand (CD40L), has been considered and tested as additional target to modulate macrophage behavior and anti-tumor immune response." (PMID 37346794, 2023). "Although cross-linking CD40 did achieve complete tumor regression in the absence of CD4+ T cells, it did occur at a slower kinetic rate compared to tumor-bearing animals having an intact CD4+ T cell population." (PMID 37655661, 2023). "Meanwhile, tumor cells in the combination groups showed a higher rate of apoptosis as detected by the TUNEL assay, as well as higher acetylation status, ubiquitination level of HP1γ, suppressed HP1γ level and FOS, JUN and CD40 expression." (PMID 36894562, 2023). "CD40 expression on the tumor epithelium showed no prognostic effect in any of the three large populations assessed." (PMID 36894898, 2023). "Aside from tumor cell-target therapeutics like anti-CD47 antibodies and PD-1 blockade, other macrophage-related checkpoints are also identified, such as CD40 agonists, B7-H4 (aka B7x, B7S1 or VTCN1) and V-domain Ig- containing suppressor of T cell activation (VISTA, aka PD-1H, DD1α)." (PMID 37426676, 2023). "Agonistic anti-CD40 cross-linking antibody fully restored CD8+ T cell-mediated tumor rejection in the complete absence of CD4+ T cells, suggesting that providing Th1-based cell help is a key feature for effective therapy even in the absence of CD4+ Tfh." (PMID 37655661, 2023). "The only significant correlation with clinicopathologic features was the association between the squamous subtype of NSCLC and higher QIF scores for CD40 in the tumor compartment when compared to the non-squamous subtypes (3C)." (PMID 36894898, 2023).
tumor (continued). "Thus, the CD40/CD40L pathway participates in the anti-microbial and anti-tumor activity of macrophages." (PMID 37143666, 2023). "Upon 7 days of treatment with 0.5–2 μM CSF1Ri± anti-CD40 mAb we observed a non-significant trend of reduced macrophage viability and a significant decrease in tumor cell viability with 0.5–2 μM CSF1Ri ± anti-CD40 mAb treatment conditions (p < 0.05)." (PMID 37346794, 2023). "Further, the addition of radiation to CD40 mAb did not significantly improve the rate of tumor burden reduction." (PMID 36658712, 2023). "When combined with radiation anti-CD40 slowed tumor progression without achieving a partial response." (PMID 37620372, 2023). "To evaluate whether local NDES CD40 mAb delivery could induce an abscopal effect, we used a bilateral KPC tumor model." (PMID 36658712, 2023). "Instead, engineered T cells + CD40 agonist, which we previously showed to promote the persistence of engineered T cells in autochthonous PDA, promoted tumor cytoplasmic Cxcl9/Cxcl10, indicating that immunotherapy alters the subcellular localization of Cxcr3 ligands in tumor cells." (PMID 36472588, 2023). "In this study, we used an innovative delivery approach to sustainably administer low‐dose agonist CD40 mAb intratumorally, which resulted in tumor elimination without adverse effects common to conventional systemic administration." (PMID 36658712, 2023). "This suggests that in the presence of tumor-derived antigens, CD40 signaling in cDC1s is critical not only for CD8+ T cell initiation but also for early activation of naïve CD4+ T cells." (PMID 37183207, 2023). "CD40 (TNFRSF5) is a co-stimulatory cell surface receptor expressed in both hematopoietic and non-hematopoietic cells, where it can activate DCs, prime tumor-specific CD8 T cells, and finally stimulate antitumor immunity." (PMID 37153589, 2023). "In EC, CD40 activation of M1-like macrophages resulted in effective tumor growth inhibition but failed to reverse the proliferative effects of M2-like macrophages." (PMID 37810971, 2023). "CD40 is a member of the TNF receptor superfamily on APC, which can enhance the expression of MHCs,81 the production of costimulatory molecules, and the interaction between T cells and DCs to improve the tumor microenvironment." (PMID 36464889, 2023). "On the other hand, tumor cell segments displayed lower levels of CD44, CD40, and CD27." (PMID 38044986, 2023). "Moreover, the combination of anti-CD40/PD-1 therapy led to an increased number of CD4+ and CD8+ T cells, CAF cells and myeloid cells in the tumor, which were shown to drive immunotherapy resistance in CCA." (PMID 36980187, 2023). "The goal of these CD40 targeted therapies, which include agonistic CD40 antibodies, bispecific antibodies with CD40 as one of the targets, and adenoviral vectors that increase CD40L expression, is to evoke a primarily tumor-specific T cell response." (PMID 36894898, 2023). "Co-expression of Fas-CD40 with either 4-1BB- or CD28-containing CARs increased in vitro efficacy by augmenting CAR T cell proliferation and cancer target cytotoxicity, and enhanced tumor killing and overall mouse survival in vivo." (PMID 37200859, 2023). "In accord, flow cytometry analysis illustrated that TAMs from tumor-bearing Irg1−/− mice manifested enhanced immunogenic antigen presentation, as evidenced by higher expression of cell surface markers, such as MHC-I, MHC-II, or Cd40." (PMID 37115931, 2023). "The hydrogel microsphere vaccine enhances in situ recruitment and amplification of tumour-resident CD103+ CD11b− cDC1s by rapidly releasing FLT3L, followed by the controlled release of CD40 agonist in the acidic TME, which further amplified activation and antigen-priming of cDC1s." (PMID 37433774, 2023).
tumor (continued). "PDT with the construct resulted in significant tumor growth inhibition as well as increased expression of CD70 and CD40 in CD11c+ DCs in tumor-draining lymph nodes and enhanced IFN-y levels in serum, suggesting that the treatment induces an antitumor immune response." (PMID 36839652, 2023). "CD40 is a member of the tumor necrosis factor (TNF) receptor superfamily that allows dendritic cells (DCs) to promote antitumor T cell activation and re-educates macrophages to destroy the tumor stroma." (PMID 35139879, 2022). "Tumor cells are also able to escape from NK lysis due to their lack of expression of costimulatory molecules, such as B7-1 (also known as CD80), B7-2 (or CD86), CD40 and CD70, that hinder the optimal activation of these cells." (PMID 35335881, 2022). "These inducible MyD88/CD40 CAR T cells exhibited superior T-cell proliferation, cytokine production, and tumor killing ability compared to second-generation CAR T cells that did not contain the inducible MyD88/CD40 molecule." (PMID 35628381, 2022). "Moreover, this biocomplex regulated the secretion of tumor-related cytokines (i.e., GM-CSF, TNF, and IL-6) and promoted the activation of immune cell surface markers (i.e., CD80+, CD86+, and CD40+)." (PMID 36059807, 2022). "TNFSF9, CD276, CD40, CD274, and CD44 expression was downregulated in cluster 6 (hypoxic tumor)." (PMID 36685583, 2022). "In addition, the expressions of CD40L, CD40 and LOX increased with the tumour grade in all patients, and higher expressions of the target genes were observed in the mesenchymal type." (PMID 35908277, 2022). "Unlike blocking tumor progression or invasion signals in part, CD40 agonism is an “ignition” signal resulting in APC activation, macrophage tumoricidal activity, and CD8+ T cell-dependent antitumor immunity." (PMID 35139879, 2022). "Moreover, some OVs have been designed to express T cell costimulatory molecules, including CD40, 4-1BB, or OX40 (CD134), to stimulate tumor-specific T cell activation and strengthen anti-tumor immunity." (PMID 36297203, 2022). "Mice with cDC1-specific inactivation of CD40 failed to reject tumors normally rejected by WT mice, in a system where tumor rejection requires both CD8 priming and CD4 help." (PMID 35543702, 2022). "The DCs present in the tumor were positive for H-2Kb, but not for CD40 or CD86, while the DCs in lymph nodes were positive for CD40." (PMID 36551577, 2022). "However, the expression of DC maturation markers, such as MHC class II and the costimulatory molecules CD86 and CD40, is reduced by the action of Tregs, which directly affects CD8+ T cell activation and the expansion of tumor-infiltrating DCs." (PMID 35205732, 2022). "CD40-activated B cells (CD40-B cells) have similarly been used by many groups as a readily available source of highly efficient APC and have been shown to be capable of priming Th1 type anti-tumor responses." (PMID 36159874, 2022). "In some cancer models, CD40-mediated activation of macrophages, which possibly mimics the effects of CD4+ T cell stimulation, has been shown to drive tumor control in an IFNγ-dependent manner, resulting in substantial remodeling and collapse of the tumor’s fibrotic network." (PMID 34282297, 2022). "Using our models, we showed that this was not the case - resection of tumor dLN does not compromise adjuvant immunotherapy, at least using anti-CD40 or immune checkpoint blockade agents." (PMID 35431929, 2022). "Among the top enriched signaling pathway network, the interactions between THBS2+ CAFs and other cells within the tumor micro-ecosystem were most mediated by THBS, followed by stromal/immune signaling pathways, e.g. THY-1, FN-1, TGF-β, IL6/4, MHC-I, VEGF, CD40, or TIGIT." (PMID 35547750, 2022). "This may reflect that gemcitabine antagonizes the ability of CD40- and ICB-based therapy to restrict tumor progression in animal models." (PMID 36143975, 2022).
tumor (continued). "It is now assumed that in the clinic the antitumoral efficacy of CD40 agonists is dependent on a proinflammatory microenvironment, which is typically not present in advanced tumor stages." (PMID 36361658, 2022). "Perhaps most striking, however, was the demonstration that blocking T cell egress from lymph nodes, the presumed site of CD40-mediated activation of DCs, did not impact either the expansion of intratumoral T cells or their ability to control tumor outgrowth." (PMID 34282297, 2022). "Combination with IL‐6 blockade is not effective for sensitizing such tumor to ICI (anti‐PD‐1/anti‐CTLA‐4), but neutralization of IL‐6 along with stimulation of CD40 can cause tumor sensitization to ICI." (PMID 35301813, 2022). "We hypothesized that CD40 ligation-induced licensing of DCs that had captured and processed antigens from neighboring CSCs would result in activation of CSC-specific anti-tumor immunity, leading to complete tumor clearance." (PMID 35788566, 2022). "The broad expression of CD40 by various immune and non-immune cells types in the tumor and in other organs is likely to contribute to the occurrence of these side effects." (PMID 35911742, 2022). "We therefore sought to enhance the tumor-killing activity of DC-CIK cells in two distinct ways: First, by promoting maturation and activation of antigen-presenting DCs through CD40 ligation, and second, by suppressing inhibitory signaling in the effector cells or reducing Tregs by CTLA-4 blockade." (PMID 36091050, 2022). "In addition to CD11c, antigen presenting (HLADR and β2M), costimulatory molecules (CD40, ICOS) as well as STING and CD68 were all upregulated in tumor compared to TAS." (PMID 36230846, 2022). "Another recent study demonstrated that an agonist of CD40 (another co-stimulatory activator of T cells), in combination with inhibitors of MEK and autophagy, activated anti-tumor immunity and inhibited PDAC growth in a mouse model indicating the potential relevance of therapeutically targeting PKCι." (PMID 35159064, 2022). "CD40 agonist primed tumor-specific CD8+ T cells independent of cDC1s, which was dependent on monocytes/macrophages." (PMID 35393950, 2022). "Our findings further unravel the multi-faceted properties of the CD40/mCD40L dyad, highlighted by the novel TNFR crosstalk that accelerates tumour cell-specific death, and may have implications for the use of CD40 as a therapeutic target." (PMID 36291141, 2022). "We did note a slight increase in proportion of cells co-expressing CD40 and CD80 in the converted tumor-migratory CD11b+ DCs, although the overall number of these cells migrating was still significantly reduced in radiation-treated animals compared with untreated controls." (PMID 35487695, 2022). "We also observed differences between in vitro and in vivo performance, such as the lack of in vivo anti-tumor efficacy for CD40." (PMID 36350984, 2022). "CD40 is a cell-surface glycoprotein that belongs to the tumor necrosis factor receptor superfamily and is expressed on APC such as dendritic cells (DC), B cells and macrophages, as well as epithelial and endothelial cells and certain types of tumor cells." (PMID 33948686, 2021). "Interestingly, unlike single-agent treatment with anti-PD-1/PD-L1 or anti-CTLA-4 antibodies, both anti-CD40 and OX40 antibodies as single agents have demonstrated efficacy in Pan02 tumor-bearing mice, in both subcutaneous and orthotopical models." (PMID 33503832, 2021). "Mature DCs loaded with PAM lysates showed an increased maturation potential, as estimated by their increased expression of CD83, CD86, CD40, IL-12/IL-10 production, and attenuated PDL1 and ILT-4 expression, compared to the DCs treated with control tumor lysates." (PMID 33915703, 2021). "In this line, it has been reported that CD40 agonist antibodies activate antitumor macrophages and other antibodies inhibit the CD47 surface molecule in tumor cells, leading to macrophage-mediated tumor cell phagocytosis." (PMID 34677429, 2021).
tumor (continued). "Furthermore, while shRNA control vector transfection responded to RGS treatment with reduced YUMM3.3 tumor growth in vivo, tumors with attenuated CD40 expression (shRNA_CDS and shRNA_UTR) were resistant to RGS-mediated inhibition of tumor growth." (PMID 34092233, 2021). "First, CD40-mediated activation of antigen presenting cells (APCs) is a prerequisite for T-cell activation and thus can promote the generation of tumor-specific cytotoxic T cells even in the absence of CD4 T-cell help." (PMID 33392713, 2021). "This key CD4+ T cell help occurs through the licensing of dendritic cells (cDC1) through their interaction with MHC II and CD40/CD40L on CD4+ T cells, which was recently demonstrated in vivo in tumors, and resulted in successful cross presentation of tumor antigens to CD8+ T cells." (PMID 33708224, 2021). "All treatments enhanced PD-L1 expression on TAMs, with variable induction of CD40 and HLA-DR; PD-L1 expression on endothelial cells and tumor cells was either absent or unchanged." (PMID 33767151, 2021). "Remarkably, one study in an in vivo PDAC model showed this efficacious anti-tumor activity to be directly mediated by CD40-expressing macrophages rather than T cells." (PMID 34439292, 2021). "The survival benefit was accompanied by a significant infiltration of IFNγ-, Granzyme B-, and TNFα-secreting effector T-cells, demonstrating that the combined use of CD40 agonist and PD1 antagonist antibodies can reprogram immune resistant tumors in favor of anti-tumor immunity." (PMID 34201127, 2021). "CD40 is a potent stimulator of APCs and myeloid cells, and its activation by CD40L has been shown to activate and license APCs to prime cytotoxic T cells, resulting in enhanced tumor immunity." (PMID 34358141, 2021). "This expansion was not an upper limit however, as the lymphoid organs of naive mice immunized intravenously with SPAS-1 (H8) peptide in a TriVax formulation containing anti-CD40 and Poly I:C57 accumulated over 40-fold more SPAS-1 specific T cells than were generated by the tumor response." (PMID 34162858, 2021). "We found that CD68 (macrophage), but not CD177 (neutrophil), is positively correlated with CD40 in both normal (r = 0.42) and tumor (r = 0.38) tissues." (PMID 34758832, 2021). "Hypothetically, the inhibition of IL-10 or the coactivation of CD40, IL-12, IL-8, and TNF-α, could repolarize these macrophages to the M1 phenotype, where reverse tumor development has been demonstrated." (PMID 34177892, 2021). "After in vitro stimulation to generate CD40+ B cells and plasma cells, these cells were transferred in mice bearing OVA+ tumors leading to antigen-specific T cell responses, with a marked decrease of tumor growth and death." (PMID 34576154, 2021). "Histological analysis of the regressed mouse and human tumors revealed a cellular infiltrate devoid of lymphocytes, reiterating CD40-induced anti-tumor activity is independent of T cells." (PMID 33503832, 2021). "Fitting with this hypothesis, the two commonly used anti-mouse CD40 agonist antibody clones, FGK45 and IC10, bind the CD40L binding site of CD40 and depend on FcR crosslinking and both show potent anti-tumor efficacy in preclinical mouse models." (PMID 33392713, 2021). "Flt3L did not affect the activation state of tumor-infiltrating cDC1s, because it did not affect the levels of CD40, CD86 or MHCII in tumor-infiltrating cDC1s." (PMID 33810248, 2021). "CD40, also known as TNFRSF5, is a co-stimulatory cell surface receptor present on antigen-presenting cells (APC), non-hematopoietic cells (e.g., myofibroblasts, fibroblasts, epithelial, and endothelial cells) and tumor cells." (PMID 34758832, 2021).